FUBP3 (far upstream element binding protein 3)
Description:
May interact with single-stranded DNA from the far-upstream element (FUSE). May activate gene expression.
Synonyms: FBP3
Tractability: PROTAC: UniProt records ubiquitination sites on it; ubiquitination databases record sites on it; its protein half-life has been measured.
Target class: Transcription factor
Gene: Protein-coding gene on chromosome 9 (130,578,965 to 130,638,354, forward strand). Ensembl gene ENSG00000107164.
Subcellular location: Nucleus
Subcellular location (Human Protein Atlas): Nucleoplasm; Cytosol
Gene Ontology:
Molecular function: protein binding; RNA binding; single-stranded DNA binding; mRNA 3'-UTR binding; nucleic acid binding
Biological process: DNA-templated transcription; positive regulation of DNA-templated transcription; positive regulation of gene expression; positive regulation of transcription by RNA polymerase II
Cellular component: cytoplasm; membrane; nucleus
Genetic constraint (gnomAD): Loss-of-function variants: 16 observed, 46.25 expected, observed/expected ratio (o/e) 0.35, 90% interval 0.23 to 0.52. The upper end of that interval is the gene's LOEUF score, 0.52, which puts it in group 2 of 6, group 1 being the genes least tolerant of losing a copy. Missense variants: 380 observed, 465.92 expected, observed/expected ratio (o/e) 0.82, 90% interval 0.75 to 0.89. Synonymous variants: 171 observed, 175.7 expected, observed/expected ratio (o/e) 0.97, 90% interval 0.86 to 1.11.
Homologues: Orthologues: chimpanzee FUBP3 (99% identical), macaque FUBP3 (99% identical), dog FUBP3 (96% identical), guinea pig FUBP3 (93% identical), mouse Fubp3 (93% identical), rat Fubp3 (93% identical), pig FUBP3 (85% identical), tropical clawed frog fubp3 (81% identical), chimpanzee FUBP3 (74% identical), zebrafish fubp3 (67% identical), rabbit FUBP3 (51% identical), Caenorhabditis elegans fubl-3 (30% identical), and 7 more. Paralogues in human: FUBP1 (59% identical), KHSRP (53% identical), IGF2BP2 (18% identical), IGF2BP1 (18% identical), NOVA1 (18% identical), PCBP4 (18% identical), IGF2BP3 (17% identical), PCBP3 (17% identical), PCBP2 (17% identical), PCBP1 (17% identical), HNRNPK (17% identical), NOVA2 (17% identical).
Diseases named in the same sentence as FUBP3 in open-access papers:
FUBP3 is named in the same sentence as 23 diseases in open-access papers, as found by Europe PMC text mining. Sharing a sentence is not in itself a finding about the gene and the disease. The quoted sentences say what the papers report.
colorectal cancer (4 papers, 2021 to 2023). A primary or metastatic malignant neoplasm that affects the colon or rectum. "CMPK2—CMPK2 is a long non-coding RNA that is typically upregulated in colorectal cancer and is positively correlated with metastases to lymph nodes and advanced stages through stimulation of FUBP3–c-Myc signaling." (PMID 38304289, 2023). "For instance, the FUBP3–c-Myc axis is activated to promote colorectal cancer progression, and FUBP3 is more frequently expressed in prostate and bladder cancer than in renal cancer." (PMID 35413821, 2022). "CMPK2 is a long noncoding RNA that promotes colorectal cancer progression by activating the FUBP3-Myc signaling axis." (PMID 34830961, 2021). "FUBP3 has been shown to interact with long noncoding RNA CMPK2 and drive colorectal cancer progression via activation of c‐Myc signalling." (PMID 36478132, 2023).
bladder cancer (3 papers, 2008 to 2023). "However, FUBP3 can promote cancer progression by activating c‐Myc in colorectal, liver, and renal cancers but not prostate or bladder cancer." (PMID 37180822, 2023).
leukaemia (2 papers, 2023 to 2025). "Additionally, a number of FUBP3-bound RNAs target were implicated with cancer-related pathways, including E2F targets, mTORC1 signaling, carcinoma, and leukemia; as well as cell cycle regulation processes such as mitotic progression and the G2/M checkpoint." (PMID 40248217, 2025). "Also, there was a significant association of decreased FUBP3 expression with increased bone marrow fibrosis which is a central pathological feature in the monitoring of leukaemias, with progressive fibrosis being an indicator of adverse outcomes in CML patients." (PMID 36478132, 2023). "Since the patients recruited in our study are yet to complete 5 years, we used cBioPortal to understand if FUBP3 expression has any effect on OS in leukaemias, including CML." (PMID 36478132, 2023). "The role of FUBP3 has not been characterized in leukaemia, and to comprehend the same, FUBP3‐siRNA mediated knockdown experiments were performed in K562 cells to mimic the conditions in CML samples." (PMID 36478132, 2023).
viral infection (2 papers, 2021 to 2025). "Most importantly, FUBP3 was found to interact with RNAs encoding proteins involved in viral infections, including HIV, as well as other infectious diseases." (PMID 40248217, 2025). "Beyond its role in HIV, FUBP3 modulates the expression of genes linked to T cell activation, inflammation, and oncogenic pathways while also recognizing numerous mRNAs associated with viral infection, cell cycle regulation, and cancer pathways." (PMID 40248217, 2025). "BHK-21 cells were cultured and infected with JEV to investigate the functional role of FUBP3 in the viral infection cycle." (PMID 34794468, 2021). "Furthermore, our findings highlight FUBP3’s possible involvement in oncogenic or inflammatory pathways, underscoring its significance beyond viral infections." (PMID 40248217, 2025). "It has been shown that FUBP3 protein is present in the cytoplasm and nucleus of cells, and it has been suggested that some viral infections may lead to redistribution of host proteins in cells." (PMID 34794468, 2021). "The identification of 346 RNAs associated with FUBP3 suggests that it may also influence cellular responses on a broader scale, including in viral infections where FUBP3 could impact the stability and replication of viral mRNA as well as the host cell response." (PMID 40248217, 2025).
brain cancer (1 paper, 2015). A primary or metastatic malignant neoplasm affecting the brain. "Furthermore, the identification of a variant locus in FUBP3 in all the brain cancers (GBM, LGG, and MB) supports the potential for tissue-specific CAML and disease linkage." (PMID 26246470, 2015). "Thus, we speculate whether FGF9 regulation could be modified due to CAML genotypes in FUBP3 and importantly in brain cancer pathogenesis." (PMID 26246470, 2015). "Unique to all of the brain cancers (GBM, LGG, and MB) was a locus in the intron of FUBP3 (9:133498230-133498244)." (PMID 26246470, 2015).
diabetes (1 paper, 2026). "At the mRNA level only borderline significant changes in Chmp3 and Fubp3 were detected using the duodenum of the pre-clinical high-fat diet C57BL/6J mouse model of pre-diabetes." (PMID 41840478, 2026).
glioblastoma (1 paper, 2022). The most malignant astrocytic tumor (WHO grade IV). "Through one-way analysis of variance comparison, compared with controls, the number of glioblastoma cells expressing FUBP3 was greater, but the color of the cell nuclei was lighter, meaning that the expression of FUBP3 in the cell nucleus of GBM tissues decreased (P < 0.05)." (PMID 35413821, 2022).
hepatocellular carcinoma (1 paper, 2020). A malignant tumor that arises from hepatocytes. "For instance, SIAH-1 has been reported to positively and indirectly regulate FBP-3 (FUBP3), which primarily supports human hepatocellular carcinoma cell proliferation, suggesting a key role in cancer development." (PMID 32391054, 2020).
HIV-1 infection (1 paper, 2025). The type species of lentivirus and the etiologic agent of acquired immunodeficiency syndrome (AIDS). "Interestingly, one of the RNAs bound by FUBP3 implicated in HIV-1 infection processes is CDK1, which also shows significant downregulation upon FUBP3 depletion." (PMID 40248217, 2025). "This suggests that FUBP3 generally promotes gene expression across the transcriptome, particularly in the context of HIV-1 infection." (PMID 40248217, 2025). "This study uncovers FUBP3’s dual role in viral activation and immune regulation, providing insights into host-virus dynamics and highlighting its potential as a therapeutic target in HIV-1 infection and related pathologies." (PMID 40248217, 2025).
lung adenocarcinoma (1 paper, 2025). A carcinoma that arises from the lung and is characterized by the presence of malignant glandular epithelial cells. "Through assays, we found that FUBP3 has an oncogenic role in lung adenocarcinoma and promotes cell proliferation, migration, and invasion." (PMID 40704413, 2025). "However, in the CPTAC database, FUBP3 protein expression is significantly elevated in lung adenocarcinoma tissues." (PMID 40704413, 2025).
systemic lupus erythematosus (1 paper, 2022). An autoimmune multi-organ disease typically associated with vasculopathy and autoantibody production. "KEGG analysis showed that FUBP3 may be significantly associated with the chemokine signaling pathway, cytokine receptor interaction, leishmania infection, the ribosome, and systemic lupus erythematosus." (PMID 35413821, 2022).
cancer (8 papers, 2008 to 2025). A tumor composed of atypical neoplastic, often pleomorphic cells that invade other tissues. "In our study, FUBP3 was expressed in the normal tissue adjacent to the cancer and in the GBM samples to varying degrees." (PMID 35413821, 2022). "Different members of the FUBP family have different functions in different cancers, and FUBP3 plays different roles in different tumors." (PMID 35413821, 2022). "However, CPTAC database analysis showed a significant increase in FUBP3 protein levels in cancer tissues." (PMID 40704413, 2025). "In summary, FUBP3 regulates the expression of numerous genes involved in cancer regulation, as well as genes pertinent to T cell activation, cell cycle processes, and TNF-α-induced inflammation via the NF-κB pathway in J-Lat 10.6, uninfected Jurkat, and uninfected primary CD4+T cells." (PMID 40248217, 2025). "Although not fully established, Fubp3 appears to possess single-stranded DNA binding activity, is involved in the regulation of gene expression, and has recently been implicated in different cancers." (PMID 36768448, 2023).
tumor (6 papers, 2008 to 2024). "Mechanistically, USP7 expression is activated by the transcription factors FUBP1 and FUBP3, and it promotes tumor progression mainly by deubiquitinating and stabilizing HIF2α." (PMID 39406703, 2024). "We herein identified a sustained USP7 expression that, transcriptionally activated by FUBP1 and FUBP3, is essential for HIF2α stabilization and tumor progression in ccRCC." (PMID 39406703, 2024). "FUBP1 is the most important member of the FBP family (which includes FUBP1, FUBP2, and FUBP3) that functions oppositely in different tumors, showing both pro‐oncogenic and tumor‐suppressive effects." (PMID 37180822, 2023). "This study is the first to suggest the tumour‐suppressive role of FUBP3 protein in CML and the association of microdeletions and decreased expression of the FUBP3 gene with adverse outcomes." (PMID 36478132, 2023). "Tumor microenvironment analysis showed that FUBP3 expression was positively correlated with the expression of CD8+ T cells, CD4+ T cells, and macrophages (P < 0.05)." (PMID 35413821, 2022). "Collectively, our results suggest that FUBP3 in GBM is a potential predictor for the malignancy of the tumor." (PMID 35413821, 2022). "The results showed that the expression of FUBP3 in the cell nuclei of GBM tissue decreased compared with that of the normal tissue adjacent to the tumor." (PMID 35413821, 2022). "Therefore, we carried out further verification and found that the expression level of FUBP3 was lower in GBM samples than in normal tissue adjacent to the tumor, and the higher the expression level of FUBP3, the longer the GBM patients survived." (PMID 35413821, 2022). "The expression of FUBP3 was positively correlated with the expression of CD8+ T cells, CD4+ T cells, and macrophages in tumor tissue, based on immunohistochemistry." (PMID 35413821, 2022). "We then considered the possible mechanism of action of FUBP3 in GBM by KEGG and GO analyses and tumor microenvironment analysis based on TCGA tumor datasets, and immunohistochemistry identified a positive correlation between immune cells and FUBP3." (PMID 35413821, 2022). "Conversely, the immune monitoring effect is weakened and tumor prognosis is poor for the FUBP3-lacking GBM group." (PMID 35413821, 2022). "Tumor microenvironment analysis showed that FUBP3 may be connected to immune infiltration, and immunohistochemistry identified a positive correlation between immune cells (CD4 + T cells, CD8 + T cells, and macrophages) and FUBP3." (PMID 35413821, 2022).
infection (2 papers, 2021 to 2025). The state of being infected such as from the introduction of a foreign agent such as serum, vaccine, antigenic substance or organism. "We also demonstrated that FUBP3 re-localized in the cytoplasm after infection with JEV and co-localized with viral proteins." (PMID 34794468, 2021). "Our findings reveal that FUBP3 positively regulates HIV-1 transcription and infection in various cell lines and primary CD4+T cells." (PMID 40248217, 2025). "Since FUBP1 has been reported to negatively regulate the infection cycle of JEV, this study focused on the possible role of FUBP3 in the JEV infection cycle." (PMID 34794468, 2021). "Moreover, numerous genes downregulated by FUBP3 depletion are directly involved with HIV transcription and/or infection." (PMID 40248217, 2025). "The cytoplasm of overexpressed FUBP3 cells had many positive stains for FUBP3, and after infection with JEV, the intracellular distribution of many FUBP3 was affected by JEV and then co-localized with the viral NS5 protein, as shown around the viral replication sites." (PMID 34794468, 2021).
FUBP3 also shares sentences with these, for which no sentence is quoted: renal carcinoma (3 papers); adenocarcinomas of the prostate (1); Alzheimer disease (1); chronic myeloid leukaemia (1); clear cell renal cell carcinomas (1); infectious disease (1); prostate carcinoma (1); renal cell carcinoma (1); triple-negative breast carcinoma (1).